CCN4 (cellular communication network factor 4)
Diseases named in the same sentence as CCN4 in open-access papers (continued):
Sharing a sentence is not in itself a finding about the gene and the disease.
atherosclerosis (5 papers, 2019 to 2024). A disease characterized by the build-up of fatty material and calcium deposition in the arterial wall resulting in partial or complete occlusion of the arterial lumen. "We have also studied the effect of increasing or deleting CCN4 on macrophage behaviour in vitro to assist with determining the underlying mechanism of action of CCN4 in the regulation of atherosclerosis." (PMID 39276419, 2024). "We used a helper-dependent adenovirus encoding CCN4 to enhance circulating levels, and CCN4-deficient mice, to monitor the effects of both increasing and knocking out CCN4 on the progression of atherosclerosis." (PMID 39276419, 2024). "These multiple possible roles for CCN4 in the different processes associated with atherosclerosis make it an intriguing candidate for further investigation." (PMID 39276419, 2024). "CCN4/WISP-1 regulates various cell behaviours that contribute to atherosclerosis progression, including cell adhesion, migration, proliferation and survival." (PMID 39276419, 2024). "As such, the pro-survival effect of CCN4 is worthy of further investigation, in a bid to find a therapeutic for atherosclerosis." (PMID 39276419, 2024). "More recently, the role of CCN4 has been studied in the cardiovascular system and in cells relevant to the study of atherosclerosis, including vascular smooth muscle cells (VSMCs) and macrophages." (PMID 39276419, 2024). "We conclude that in an atherosclerosis model the most important action of CCN4 is the effect on cell apoptosis." (PMID 39276419, 2024). "The objective of this study was to determine the role of CCN4 in atherosclerosis." (PMID 39276419, 2024). "It has been reported that CCN4 (cellular communication network factor 4) promotes the migration and proliferation of vascular smooth muscle cells by interacting with α5β1 integrin, which plays a vital role in the occurrence and development of atherosclerosis." (PMID 36358920, 2022). "However, we know that CCN4 also has some effects that may contradict this in human atherosclerosis." (PMID 39276419, 2024). "It is possible that in human atherosclerosis CCN4 may have a different effect, as human atherosclerosis may be initiated via neointimal formation rather than macrophage foam cell accumulation." (PMID 39276419, 2024).
esophageal squamous cell carcinoma (5 papers, 2015 to 2025). Esophageal squamous cell carcinoma (ESCC) is a type of esophageal carcinoma (EC) that can affect any part of the esophagus, but is usually located in the upper or middle third. "Previous studies have reported abnormal expression of WNT1-inducible signaling pathway protein 1 (WISP1)/Cellular Communication Network Factor 4 (CCN4) in esophageal squamous cell carcinoma (ESCC)." (PMID 40771797, 2025).
chondrosarcoma (4 papers, 2013 to 2026). A malignant cartilaginous matrix-producing mesenchymal neoplasm arising from the bone and soft tissue. "CCN4 (WISP-1) increases the activity of MMP-2, via the αvβ1 integrin receptor and the FAK, MEK, ERK, IKKα/β, and NF-κB pathways, leading to enhanced migration of human chondrosarcoma cells." (PMID 24490159, 2013).
lung adenocarcinoma (4 papers, 2020 to 2026). A carcinoma that arises from the lung and is characterized by the presence of malignant glandular epithelial cells. "Further analysis clarified that V. parvula promoted activation of the NF-κB pathway via Nod2/CCN4 signaling, which promoted lung adenocarcinoma cell proliferation." (PMID 37452162, 2023). "Thus, V. parvula mediates activation of the Nod2/CCN4/NF-κB signaling pathway to promote non-small cell lung adenocarcinoma progression, thereby providing a potential target for diagnosing and treating lung adenocarcinoma." (PMID 37452162, 2023). "Further analysis of differential gene expression and KEGG enrichment by transcriptome sequencing revealed that V. parvula induced CCN4 expression and activated NOD-like receptor and NF-κB signaling pathway in lung adenocarcinoma cells." (PMID 37452162, 2023).
lymph node metastasis (4 papers, 2017 to 2021). "Further, WISP-1/CCN4 promotes VEGF-C dependent lymphangiogenesis by inhibiting miR-300 (3′-UTR binding repressor of VEGF-C) in vitro via the integrin αvβ3/integrin-linked kinase (ILK)/Akt signalling pathway, and it has been suggested as a potential biomarker for predicting lymph node metastasis." (PMID 34205668, 2021).
Arthritis (3 papers, 2013 to 2024). Inflammation of a joint. "Because no research has assessed the role of CCN4 in RA, a better understanding of the mechanisms through which CCN4 proteins influence the pathophysiological mechanisms associated with various types of arthritis is needed." (PMID 39262670, 2024). "It has been recently reported that CCN4 is involved in the pathogenesis of arthritis, because CCN4 was able to elicit the release of MMPs and aggrecanase from macrophages and chondrocytes to cause cartilage damage." (PMID 23343403, 2013).
fibrosis (3 papers, 2021 to 2022). the formation of excess fibrous connective tissue in an organ or tissue in a reparative or reactive process. "To clarify this, we examined the association between CCN4 in circulation and its hepatic expression with fibrosis markers in liver samples from severely obese subjects without advanced liver cirrhosis." (PMID 33946738, 2021).
liver cirrhosis (3 papers, 2018 to 2025). "We showed for the first time that, in severely obese subjects without advanced liver cirrhosis, hepatic CCN4 expression is associated with BMI, expression of fibrosis markers, and ECM turnover enzymes in liver samples." (PMID 33946738, 2021).
Nephroblastoma (3 papers, 2021 to 2022). An embryonal neoplasm characterized by the presence of epithelial, mesenchymal, and blastema components. "The CCN family includes CCN1/CYR61 (cystein-rich 61], CCN2/CTGF (connective tissue growth factor), CCN3/NOV (nephroblastoma overexpressed), and also CCN4/WISP-1, CCN5/WISP-2, CCN6/WISP-3 (Wnt-inducible secreted proteins)." (PMID 34940056, 2021).
type 2 diabetes (3 papers, 2020 to 2021). "In a cohort of subjects with type 2 diabetes, the circulating CCN4 levels correlated positively with fat mass, serum leptin, resistin, and visfatin levels, suggesting that CCN4 may contribute to the metabolically-induced tissue inflammation." (PMID 33946738, 2021).
cardiac hypertrophy (2 papers, 2021 to 2022). "Other studies in models for chronic cardiac failure indicate that Ang-II mediates cardiac hypertrophy through the induction of CCN4/WISP-1." (PMID 34063397, 2021).
Myocardial fibrosis (2 papers, 2013 to 2026). "WISP1/CCN4 is a stress-responsive matricellular protein that bridges metabolic inflammation and myocardial fibrosis." (PMID 41596265, 2026).
non-small cell lung adenocarcinoma (2 papers, 2023 to 2025). Type of epithelial lung cancer arising from glandular origin. "V. parvula mediates activation of the Nod2/CCN4/NF-κB signaling pathway to promote non-small cell lung adenocarcinoma progression." (PMID 40391224, 2025). "Furthermore, Veillonella has been associated with activation of tumor-promoting pathways, including PI3K and the Nod2/CCN4/NF-κB axis, which may contribute to inflammatory responses and proliferation in non-small cell lung adenocarcinoma." (PMID 40391224, 2025).
aneurysm (1 paper, 2021). Bulging or ballooning in an area of an artery secondary to arterial wall weakening. "While conversely the CREB-dependent upregulation of CCN4 was lost with age in mice, so as aneurysm susceptibility increases with age, these patients may have lower active levels." (PMID 34080128, 2021). "These multiple potential roles for CCN4 in the processes associated with aneurysm progression indicate that CCN4 deletion may suppress aneurysm formation." (PMID 34080128, 2021). "Since CCN4 regulates cell migration, proliferation and apoptosis, processes involved in aneurysm progression, it is a potential regulator of aneurysm progression." (PMID 34080128, 2021). "The rupture rate, number of ruptured aneurysms, vessel thickness and vessel wall area in both the thoracic and abdominal portions of aortae were all significantly reduced in the CCN4−/−ApoE−/− mice compared to CCN4+/+ApoE−/− controls." (PMID 34080128, 2021). "This study illustrates that deletion of CCN4 leads to a retardation of aneurysm progression in the thoracic and abdominal aortae of ApoE−/− knockout mice." (PMID 34080128, 2021). "CCN4 has many roles in the cardiovascular system and in cells that are involved in aneurysm formation, including vascular smooth muscle cells (VSMCs) and macrophages." (PMID 34080128, 2021). "Mice received Angiotensin II infusion and high fat diet feeding to induce aneurysm formation and the effect of CCN4 deletion was evaluated." (PMID 34080128, 2021). "This indicates that aneurysm progression was retarded in the aortae of CCN4−/−ApoE−/− mice compared to control mice." (PMID 34080128, 2021). "We investigated the role of CCN4 in a mouse aneurysm model, using apolipoprotein-E knockout (ApoE−/−) mice fed high fat diet and infused with Angiotensin II (AngII)." (PMID 34080128, 2021). "Deletion of CCN4 significantly reduced the number of ruptured aortae, both thoracic and abdominal aortic area, and aneurysm grade score, compared to controls." (PMID 34080128, 2021). "CCN4 positively correlated with both weight, dietary fat and leptin in patients, suggesting it would be increased in those vulnerable to aneurysm." (PMID 34080128, 2021). "Inhibition of CCN4 could offer a potential therapeutic approach for the treatment of aneurysms." (PMID 34080128, 2021). "In summary, absence of CCN4 reduced aneurysm severity and improved aortic integrity, which may be the result of reduced macrophage infiltration and cell apoptosis." (PMID 34080128, 2021).
aortic aneurysm (1 paper, 2021). A ruptured aneurysm located in the wall of the proximal portion of the descending aorta proceeding from the arch of the aorta. "Elevated circulating levels of CCN4 could therefore be a contributing factor in the initiation of aortic aneurysms, particularly as both weight and BMI are risk factors for development of AAA and weight was correlated to CCN4." (PMID 34080128, 2021).
aspergillosis (1 paper, 2018). Aspergillosis is an infection, growth, or allergic response caused by the Aspergillus fungus. "Herein, we also confirmed by ELISA assay an overexpression of the Wnt1-inducible-signaling pathway protein 1 (Wisp-1), also known as CCN4 in humans, during experimental aspergillosis." (PMID 30040865, 2018).
astrocytoma (1 paper, 2025). "Many studies on MYBL2, E2F7, CCN4, and MET genes promote tumor progression by promoting tumor proliferation, differentiation, and migration, which may also contribute to the malignant progression of IDH-mutant astrocytoma." (PMID 41460424, 2025).
myocardial ischemia (1 paper, 2022). A disorder of cardiac function caused by insufficient blood flow to the muscle tissue of the heart. "Similar to CCN2, myocardial CCN1 and CCN4 also respond as immediate early genes and reach peak levels of expression during the inflammatory phase after onset of myocardial ischemia." (PMID 34854055, 2022).
tumor (117 papers, 2003 to 2026). "CCN4 is strongly associated with tumor progression and malignancy, promoting cell proliferation, adhesion, migration, invasion, and epithelial-mesenchymal transition via specific signaling pathways." (PMID 38994113, 2024). "A xenograft study by the same authors further revealed that inhibition of the Wnt/β-catenin/CCN4 pathway disrupts the growth of GSCs and induces apoptosis of tumour-associated macrophages." (PMID 36555253, 2022). "Among these, cellular communication network factor 4 (CCN4), encoded by WISP1, is a tumor growth and metastasis suppressor protein that was previously considered essential for endochondral ossification in CS." (PMID 41268214, 2025). "Jia and colleagues disclosed that tumor cell–secreted matricellular protein WISP1 (CCN4) directly bound to collagen I to promote its linearization in vitro (in the absence of cells) and in vivo in tumors." (PMID 41100460, 2025). "Within the CCN family, WISP1 (CCN4) has emerged as a particularly intriguing protein due to its critical involvement in tumor biology and Wnt‐1‐induced signaling pathways." (PMID 40542654, 2025). "XHP intervention resulted in downregulation of these tumor suppressors (CCND2, PRKCG, CCN4) in tumor tissues and PC-3, DU145 cell lines, revealing XHP's regulatory role in the Wnt pathway." (PMID 38994113, 2024). "Treatment with CCN4 yielded the most promising results, with an approximately 69% decrease in tumor weight compared to NK92 cells and a 33% decrease compared to CCN1." (PMID 38694508, 2024). "Immunohistochemistry (IHC) analysis supported these findings, revealing increased CD56, perforin, and granzyme B protein expression, indicating CCN4-induced tumor necrosis and upregulated NK cell infiltration." (PMID 38694508, 2024). "Strikingly, the survival of tumour-supportive macrophages is also facilitated by the CCN4/ITGα6β1/Akt pathway but via a paracrine signalling loop (Molecular event 32)." (PMID 36555253, 2022). "CCN4 is highly expressed in tumor tissues, and its high expression level significantly lowers the overall survival rate." (PMID 34031366, 2021). "Loading-driven dopamine downregulated Lrp5 in 4T1Br brain-metastasized tumor cells via dopamine receptor D1, followed by a reduction in CCN4, an oncogene inducible by Wnt signaling." (PMID 34031366, 2021). "Increased expression of CCN1, CCN2, CCN3 and CCN4 is closely related with cell adhesion, proliferation and migration, and thus they can contribute directly to tumorigenesis, tumor development and metastases." (PMID 34940056, 2021). "A cytokine array analysis revealed that the reduction in CCN4 was critical for loading-driven, dopamine-mediated tumor suppression." (PMID 34031366, 2021). "Overexpression of CCN4/WISP1v is associated with lymphatic and perineural invasion of CCA tumor cells and a poor clinical prognosis." (PMID 27829832, 2016). "Injections of CCN4 neutralizing antibodies were shown to reduce local tumor growth in a mouse xenograft model." (PMID 24551846, 2014). "A recent study by Tao and colleagues has demonstrated that CCN4, also known as Wnt1-inducible signaling pathway protein-1 (WISP1) is preferentially released by GSCs leading to a tumour-supportive cellular environment which fosters survival of both GSCs and tumour-associated macrophages." (PMID 36555253, 2022). "CCN2 and CCN4 were highly expressed in tumor, and CCN1, 3, 5 were increased in the normal sample." (PMID 36589241, 2022). "Yet, the dependence on tumor size could be a confounding factor in addition to CCN4 expression that could skew the results." (PMID 35418177, 2022). "The participation of CCN4 in cancer development has been reported by many previous studies, which showed that CCN4 serves as a tumor promoter in colorectal, breast, pancreatic, and lung cancer by enhancing cell migration and promoting epithelial-mesenchymal transition (EMT)." (PMID 33833779, 2021).
tumor (continued). "The results of these bioinformatics analyses suggest that CCN4 mainly acts as a tumor promoter." (PMID 33833779, 2021). "Furthermore, in addition to the transcript level, the copy number of the CCN4 gene was elevated in tumor tissues." (PMID 34031366, 2021). "Our previous study has shown confined staining of CCN4, CCN5 and CCN6 at the cell membrane in normal colorectal epithelial cells, while an increased staining of CCN4 and CCN6 was seen in CRC tumours." (PMID 28412738, 2017). "Membrane staining of CCN4, CCN5 and CCN6 were reduced in CRC tumours, with an elevated cytoplasmic staining of CCN4 and CCN6 but not CCN5." (PMID 28412738, 2017). "Consistent with previous reports detailing overexpression of CCN2/CTGF and CCN4/WISP1v in CCA, we detected significant overexpression of these two transcripts in all tested tumor tissues from our tumor samples." (PMID 27829832, 2016). "IFNγ ELISpots were used to quantify the CD8+ T cell functional response to the different tumor targets in the presence or absence of tumor-produced CCN4 protein." (PMID 35418177, 2022). "Overall, the presence of tumor-conditioned media and not CCN4 protein influenced T cell proliferation, which was consistent with the DAGs." (PMID 35418177, 2022). "In the CCA tumor setting, only CCN2/CTGF and CCN4/WISP1v have been studied." (PMID 27829832, 2016). "CCN4, also referred to as WISP1 (Wnt1-inducible signaling pathway protein-1), is secreted by GSCs to bind with integrin α6β1, thereby activating the Akt pathway to enhance GSC proliferation and microglia viability, creating a tumor-supportive cellular environment." (PMID 37700840, 2023). "Later, the same research group found that tumour secreted WISP-1/CCN4 promotes angiogenesis in oral SCC by upregulating VEGF-A via the αvβ3/FAK/c-Src pathway, which transactivates the EGFR/ERK/HIF1-α signalling pathway in oral SCC cells and increases angiogenesis-related tumour growth in vivo." (PMID 34205668, 2021).